TRAF1 (TNF receptor associated factor 1)
Diseases named in the same sentence as TRAF1 in open-access papers (continued):
Sharing a sentence is not in itself a finding about the gene and the disease.
uveitis (1 paper, 2021). An inflammatory process affecting a part of or the entire uvea. "The TRAF1/C5 variants are located near genes encoding for the complement component 5 and the TNF-receptor associated factor 1, a negative regulator of the TNF pathway, underscoring the role of TNF signaling in JIA associated uveitis." (PMID 34438537, 2021). "Retrospective analysis of sequence variants in six genes (PTPN22, STAT4, TRAF1/C5 locus, TGFB, TNFAIP3, and C12orf30) associated with JIA or other autoimmune/inflammatory conditions did not reveal association with uveitis across all JIA sub-forms." (PMID 34438537, 2021).
cancer (30 papers, 2004 to 2025). A tumor composed of atypical neoplastic, often pleomorphic cells that invade other tissues. "To date, there are 139 different mutations of the TRAF1 gene detected in human cancers, comprising 80% (111/139) mutations that alter the protein sequence of TRAF1 and 20% (28/139) coding silent mutations." (PMID 30294322, 2018). "Only 29% (32/111) of the coding-altering mutations of TRAF1 are recurrent and have been detected in at least two patients with various cancers." (PMID 30294322, 2018). "Co-culture of melanoma cells with endothelial cells composing the abluminal surface of blood vessels, was demonstrated to induce the expression of genes linked to cancer cell migration (CCL2, ICAM1), cancer progression (TRAF1, SERPINB2) or stem cell properties (PDGFB; CFDP1)." (PMID 34604096, 2021). "Some of the transcription factors that were specifically expressed in OS-DW cells were ATF6, CDX2, FOSL1, PRDX3, FZD6, MYNN, TRAF1 which are known to regulate pathways implicated in cancers like, Wnt/Hedgehog/Notch signaling, MAPK signaling, Apoptosis and mTOR signaling." (PMID 31690262, 2019). "At the same time, TRAF1 is a specific target of activated caspases for the apoptosis induction in cancer cells playing a role as a link between caspases and the TNF receptors." (PMID 39009887, 2024). "We sourced TRAF family gene expression RNA sequencing data (TCGA data) from the UCSC database, specifically examining TRAF1 expression across various cancer types." (PMID 38825674, 2024). "Simultaneously, TRAF1 acts as a specific target of activated caspases, contributing to apoptosis induction in cancer cells and serving as a link between caspases and TNF receptors." (PMID 39009887, 2024). "TRAF1- TRAF7 were shown to be differentially expressed in various human cancers, and upregulation of TRAF expression was observed in tumor tissues compared to normal tissues in multiple cancer cohorts." (PMID 37389738, 2023). "Conversely, TRAF1 is dysregulated in cancer, where it likely contributes to a positive feedback loop that perpetuates NF-κB signaling and survival of cancers of mature B cells." (PMID 30619326, 2018). "Further investigation of these signaling pathways using TRAF1−/− or TRAF1-transgenic animal models would provide new insights on the roles and mechanisms of TRAF1 in cancer pathogenesis." (PMID 30294322, 2018). "According to the TCGA and COSMIC datasets of sample size n > 100, the frequency of genetic alterations of TRAF1 is generally <4% in human cancers." (PMID 30294322, 2018). "TRAF1 also contributes to survival of EBV-dependent cancers through enhancing LMP1- mediated survival signaling." (PMID 30619326, 2018). "In this study, TRAF1 was found to function as an oncogene in several cancers." (PMID 38825674, 2024). "In light of the absence of comprehensive research on the association between TRAF family genes and cancer, this review delves into the clinical characteristics and prognostic significance of TRAF family genes (TRAF1–7) in pan-cancer samples, utilizing data from The Cancer Genome Atlas (TCGA)." (PMID 38825674, 2024). "An interesting question follows: Does TRAF1 have a similar role in HPV-dependent cancers, as well?" (PMID 36142875, 2022). "Additionally, TRAF1 can contribute to chronic viral infection and limit inflammation, contributing to the survival of Epstein-Barr virus dependent cancers." (PMID 36142875, 2022). "As others have shown that, TRAF1 could activate the NF-κB signaling pathway and promotes cancer development." (PMID 34749775, 2021). "New research has also shown that TRAF1 affects the cell cycle in cancer in a CDK4‐dependent manner." (PMID 33452764, 2021). "Gene amplification is the most common TRAF1 genetic alteration in human cancers." (PMID 30294322, 2018). "Besides, TRAF1 overexpressed and played a critical oncogenic role in other types of cancers." (PMID 34759347, 2022).
cancer (continued). "Interfering with TRAF1 in this process could break the cycle of NF-κB activation in these cancers." (PMID 30619326, 2018). "This is an important cytokine that plays a role in cancer, with two protein families implicated in the signaling mediated by the TNF receptor: 1) death-domain proteins, such as TRADD, FADD, TNFR1, RIP; and 2) TRAF domain-containing proteins, such as TNFR2, CD40, TRAF1, TRAF6." (PMID 26143641, 2015). "In the cancer pathway, five genes (WNT1, DLL, TRAF1, GST, and GADD45) were upregulated, while CASP3, IKBKA, STAT5A, RPS6KA5, BIRC5, BIRC2/3, and SKP2 were downregulated." (PMID 40723320, 2025). "Then, we observed that the expression of TRAF1 and TYK2 was lower in the cancer tissues than in the adjacent tissues, however, the expression level of MET is the opposite." (PMID 38363947, 2024). "This analysis revealed that TRAF1, TRAF2, TRAF3, TRAF4, TRAF6, and TRAF7 exhibit higher expression levels in cancer tissues, whereas TRAF5 is expressed at lower levels in these tissues." (PMID 38825674, 2024). "The analysis of 33 cancer types revealed that TRAF2, TRAF3, TRAF4, and TRAF7 are predominantly overexpressed, whereas TRAF1, TRAF5, and TRAF6 exhibit lower expression levels." (PMID 38825674, 2024). "Our findings support the proposal that β-carotene has anti-cancer activity by reducing NADPH oxidase-mediated production of ROS, NF-κB activation and NF-κB-regulated TRAF1 and TRAF2 gene expression, and hyper-proliferation in AGS cells." (PMID 31835889, 2019). "Gain-of-function alterations (gene amplification and overexpression) are common for TRAF1, TRAF4, TRAF5, and TRAF6 in human cancers, and are also identified for TRAF2 in epithelial cancers." (PMID 30294322, 2018). "TRAF1 plays a pivotal role in pro-survival signal transduction downstream of TNFR superfamily members and has potential as a molecular therapeutic target for various human cancer types." (PMID 39439891, 2024). "The effects of these nutrients may rely on their direct antioxidant effects and their anti-cancer activity by reducing NADPH oxidase-mediated production of ROS, NF-κB activation, and NF-κB-regulated TRAF1/2 gene expression and anti-inflammatory effects at the molecular/cellular level." (PMID 38068839, 2023). "Compared to uninfected cancers, the infected cancers had significant upregulation of nine cellular factors (FCER2, MS4A1 (CD20), PLUNC, TNFSF9, TRAF1, CXCL11, IFITM1, PPARG, and FCRL3), implying that EBV is not an innocent bystander with respect to biochemical impact." (PMID 22929309, 2012).
tumor (28 papers, 2006 to 2026). "The overexpression of another hub gene TRAF1 (TNF Receptor-Associated Factor 1) was found to inhibit apoptotic cell death of CD8 ( +) T lymphocytes triggered by antigens in tumor transgenic mice." (PMID 37926766, 2023). "TRAF1 deficiency reestablished B cell homeostasis and significantly delayed the tumor development in p80HT mice (unpublished data)." (PMID 22642622, 2012). "Further studies are required to determine whether TRAF1 associates with LUBAC in the context of NPC, whether TRAF1 or LMP1 co-localize with M1- or K63-chains in NPC tumor samples, and whether HOIP depletion is toxic to EBV+ NPC cells in culture." (PMID 25996949, 2015). "Among the primary tumor samples, AKAP9, KDM2B, MAGED1, MKI67, PCLO, and TRAF1 mutations were identified." (PMID 41614915, 2026). "Among the 95 primary tumor samples, AKAP9, KDM2B, MAGED1, MKI67, PCLO, and TRAF1 mutations were identified as single-occurrence events and were absent in the metastatic samples." (PMID 41614915, 2026). "Mechanistic studies revealed that Butein markedly downregulated the protein and mRNA expression of TWEAK, FN14, and TRAF1/2 in tumor tissue, and decreased serum levels of NF-κB-related inflammatory factors, including IL-1β, IL-6, IFN-γ, and TNF-α." (PMID 41458609, 2025). "Among risk factor genes, IL11, TRAF1, and DHRS2 were upregulated in the docetaxel-resistant group, indicating consistency with progression of tumour docetaxel resistance and poor prognosis." (PMID 38429845, 2024). "Among these genes, SPINT2, LNX1, FOXA2, and SOSTDC1 were reported to be related to tumor progression, whereas TYROBP, TREM2, IL23R, CSF2RB, TRAF1, and TGFBR1 were closely associated with immune response." (PMID 36611170, 2023). "While TRAF2 and TRAF3 have oncogenic and tumor-suppressive activities, TRAF1 and TRAF5 function as oncogenes." (PMID 37389738, 2023). "A previous study has found that TNFR2 suppresses the NK cell growth by activating the BIRC3/TRAF1 signaling pathway and promoting the immunosuppressive function of NK cells in the tumor microenvironment." (PMID 35494080, 2022). "We further showed that the effects of enhanced colony formation, cell proliferation, and subcutaneous xenograft tumor growth induced by overexpression of FXR1 were largely inhibited upon TRAF1 silencing in vivo and in vitro." (PMID 35194031, 2022). "We report the case of an ALCL patient whose tumor harbored the newly recognized TRAF1-ALK fusion and describe the clinical outcome after treatment with an ALK inhibitor." (PMID 26187744, 2015). "TRAF1 mRNA expression in the SCC tumor center was 9.62±2.18-fold higher than in normal skin (p<0.01) and also significantly higher than in the tumor center of BCCs (3.40±2.36, p<0.05)." (PMID 22808251, 2012). "Among the genes involved in the extrinsic route, TRAIL-R1 (DR4) and TRAIL-R2 (DR5) were expressed at the highest level in both low and high MKI tumours, followed by TRAF-1, TRAF-6, Fas and Fas-ligand." (PMID 16755292, 2006). "Moreover, primary tumor samples had exclusive mutations in AKAP9, KDM2B, MAGED1, MKI67, PCLO, and TRAF1." (PMID 41614915, 2026). "METTL14 affects tumor angiogenesis in a manner that is related t to TRAF1." (PMID 38053093, 2023). "In the Balb/c nude mouse model, we further proved that the enhancement of subcutaneous xenograft tumor growth induced overexpression of FXR1 could be restored by TRAF1." (PMID 35194031, 2022). "It remains to be determined whether the FXR1/TRAF1 axis, shown here, is indeed essential to promote tumor formation." (PMID 35194031, 2022). "In addition, our in vivo study also confirmed that TRAF1 KD substantially reduced MM tumor formation in xenograft mice." (PMID 34759347, 2022). "Finally, we evaluated the effect of the DNMT1/miR-378a-3p/TRAF1/p65 axis on tumor growth and angiogenesis in vivo." (PMID 34749775, 2021). "TRAF1 expression is higher in EBV-positive Hodgkin lymphoma than in EBV-negative tumor samples." (PMID 25996949, 2015).
tumor (continued). "In this report we describe an additional ALCL patient whose tumor contained a TRAF1-ALK fusion." (PMID 26187744, 2015). "Besides these mechanisms, other undiscovered tumor-promoting targets of TRAF1 might exist in MM cells, which requires systematic exploration." (PMID 34759347, 2022). "Furthermore, increase in the expression of other molecules associated with the Fas receptor such as Traf1 and Fas (TNFRSF6)-associated via death domain (FADD) leading to activation of caspase-8 was also observed in PC3 cells and/or tumor lysates with simvastatin treatment." (PMID 22974127, 2012). "Experimental data further confirmed that Butein markedly downregulated the protein and mRNA expression levels of TWEAK, FN14, TRAF1, TRAF2, and TRAIL-R3 in cSCC tumor tissue." (PMID 41458609, 2025). "In the context of HNSC, our findings indicate that TRAF1 and TRAF5 act as tumor suppressors, whereas TRAF2 emerges as an oncogenic factor." (PMID 38825674, 2024). "METTL14-mediated m6A modification promotes the stability of the TRAF1 mRNA in an IGF2BP2-dependent manner, thereby significantly promoting tumor angiogenesis." (PMID 38053093, 2023). "TNFR2 can also induce BIRC3/cIAP2 transcripts dependent on TRAF1 and decrease the transcription and expression of NKp46/NCR1, leading to tumor deterioration in mice and adverse outcomes in patients with gastrointestinal stromal tumors." (PMID 35494080, 2022). "In complete agreement with our epigenetic profiling data, gene expression of FAS, FASLG, TNFSF10, TRAF1 and TRAF2 was higher in the clusters corresponding to dysfunctional tumor-infiltrating CD8+ T cells." (PMID 35668194, 2022). "It is also shown that tumor cells cotreated with TS at 1 μg/ml or TRAIL at 25 ng/ml downregulate the expression of STAT3 target genes (cFLIP, Bcl-xL, ICAM1, VEGF, TRAF1 and the chemokine receptor CXCR4)." (PMID 34543231, 2021). "The analysis of intra-tumor signaling pathways showed that 1-MT and tumor lysate significantly reduced PDL-1, NF-κβ2, TRAF1, β-Catenin, and IKKβ as presented in." (PMID 29959375, 2018). "Similarly, as the concentration of Butein increased, the protein expression levels of TRAF1 and TRAF2 in tumor tissue declined correspondingly." (PMID 41458609, 2025). "Subsequently, we examined whether Butein affects the expression levels of the downstream proteins TRAF1 and TRAF2 in the TWEAK/FN14 signaling pathway within tumor tissue." (PMID 41458609, 2025). "In addition, the expression levels of ORC1, TNFRSF12A, TRAF1 and TIAM1 were also positively correlated with tumor grade to a certain extent." (PMID 37005685, 2023). "Hence, evaluating the expression of TRAF1 may be helpful to identify patients who could benefit from sunitinib therapy before formulating personalized treatment strategies Recently, AAVs have been increasingly employed to deliver therapeutic genes to in vivo preclinical tumor models." (PMID 35538475, 2022). "IHC was carried out to detect DNMT1, TRAF1, p65, VEGF and CD34 in tumor tissues." (PMID 34749775, 2021). "In order to investigate FXR1 and TRAF1 expression in paired UCB tissues from SYSUCC, we collected another eight paired UCB and paracancerous tissues and found the protein levels of both FXR1 and TRAF1 were frequently upregulated in tumor tissue compared with paracancerous tissue." (PMID 35194031, 2022). "Specifically, within PAAD, TRAF1 and TRAF3 demonstrated positive correlations with stromal, immune, and estimated scores while showing negative correlations with tumor purity." (PMID 38825674, 2024).
infection (23 papers, 2008 to 2025). The state of being infected such as from the introduction of a foreign agent such as serum, vaccine, antigenic substance or organism. "TRAF1-deficient mice had a smaller area of ulcer after infection for 3, 5, or 7 days compared to WT mice." (PMID 32093731, 2020). "TRAF1-deficient mice demonstrated improved control of Candida albicans intradermal infection, and concomitant increase in neutrophil recruitment and reduction in fungal burden." (PMID 32093731, 2020). "Compared to WT mice, TRAF1-deficient mice had more neutrophils in their skin tissue after infection." (PMID 32093731, 2020). "By assessing the extent of ulceration, scab, erythema, and nodule, we found that TRAF1-deficient mice had less severe clinical symptoms after infection for 3 and 7 days, compared to WT controls." (PMID 32093731, 2020). "Infection with R. conorii resulted in an increased abundance of mRNA of TNF receptor-associated factor 1 (TRAF1), which is reported to bind to TNFR2." (PMID 31024862, 2019). "By contrast, in the resistant BXD strains, most of the tested genes showed a decrease (23 genes) in expression levels post-infection with few exceptions (five genes) e.g. TNF receptor associated factor 1 (Traf1)." (PMID 18421376, 2008). "Meanwhile, an in vitro experiment also showed that increased TRAF1 expression resulting from the infection of adenovirus-harboring human TRAF1 cDNA (Ad-TRAF1) presented more neuronal apoptosis than decreased TRAF1 expression caused by treatment with TRAF1 short hairpin RNA (Ad-shTRAF1)." (PMID 33224951, 2020). "Meanwhile, while IgG-treated TRAF1-deficient mice showed a significant reduction in fungal burden than the WT controls after infection for 3 days, TRAF1-deficient mice treated with Ly6G antibody exhibited uncontrolled fungal growth 3 days post-infection, just like the control WT mice." (PMID 32093731, 2020). "In vivo, the immunofluorescence of TRAF1, 4-1BB and NF-κB p65 at vacA+Hp colonization sites was increased, and TRAF1 expression increased gradually with prolonged infection, correlating with exacerbated gastric mucosal inflammation and damage." (PMID 41136917, 2025). "In summary, these results demonstrated that infection with a virulent CSFV Shimen strain can induce the expressions of TRAF1, RIG-I, MAVS, IRF1, and ISG15." (PMID 38995016, 2024). "Infection with P. gingivalis dramatically increases A20 expression in innate immune cells, which subsequently interacts with TRAF1 and TRAF2 to form a ubiquitin-editing complex to prevent K63 polyubiquitin chain synthesis by TRAF6." (PMID 35588785, 2022). "In the present study, we established a mouse model of C. albicans intradermal infection and investigated the role of TRAF1 in antifungal immune response." (PMID 32093731, 2020). "TRAF1-deficiency led to a significant reduction in fungal burden after infection for 3 days, indicating a critical role for TRAF1-regulated immune response in the eradication of invaded C. albicans." (PMID 32093731, 2020). "Early in infection, TRAF1 is highly expressed in CD8 T cells responding to HIV, consistent with their activated phenotype." (PMID 30619326, 2018). "However, with progression of infection, TRAF1 levels are decreased in HIV-specific CD8 T cells in donors followed longitudinally." (PMID 30619326, 2018). "However, when challenged with OGD, Ad-TRAF1 infection, which increased TRAF1 expression by ~2.4-fold, led to fewer viable neurons and increased lactate dehydrogenase (LDH) release at the different time points." (PMID 24284943, 2013). "The balanced upregulation of pro-apoptotic (FAS, BBC3) and anti-apoptotic (BCL2A1, TRAF1) genes in TIGR4-infected cells likely mitigates extensive cell death, enabling Spn to maintain host cell viability for sustained infection." (PMID 40475528, 2025).
infection (continued). "Numerous host proteins were upregulated upon infection with Francisella, ranging from immune-related proteins to metabolic enzymes, including notably IRG1, MARCO, Rilpl2, C3, PcgF5, MT1, TRAF1, GBP2 and Fas." (PMID 38565565, 2024). "ii) TLR3, a receptor for viral dsRNA, displayed a strong reduction in influenza virus and icMERS infection, while TICAM1, TRAF1, TRAF2, TRAF3 and TRAF6, adaptors responsible for TLR3, changed in an opposite direction with TLR3." (PMID 34248940, 2021). "Interestingly, DVG-mediated upregulation of TNFR2 signaling was controlled by MAVS, as MAVS KO cells showed impaired upregulation of surface TNFR2 expression and blunted expression of the pro-survival genes TRAF1, BIRC3, and TNFAIP3 upon infection with SeV HD." (PMID 28986577, 2017). "Venn diagram analysis showed that among the common DGEs in the 3 h and 12 h infection groups compared with the control group, 11 differential genes were enriched in the NF-κB signaling pathway, including CXCL8, IL-1β, CCL4, IκBα, TNF, NF-κB, CFLAR, PTGS2, TRAF1, PLAU, and IL-1β2." (PMID 35215890, 2022).